ABCG2 (ATP binding cassette subfamily G member 2 (JR blood group))
Diseases named in the same sentence as ABCG2 in open-access papers (continued):
Sharing a sentence is not in itself a finding about the gene and the disease.
cancer (continued). "To examine the effect of ABCB1 and ABCG2 on the chemosensitivity of human cancer cell lines to citarinostat, we determined the cytotoxicity of citarinostat in multiple pairs of ABCB1- or ABCG2-overexpressing multidrug-resistant cancer cell lines and the respective drug-sensitive parental lines." (PMID 33807514, 2021). "In cancer patients, a combination of VKNG-1 and ABCG2 substrate drugs could be a beneficial treatment option for cells with high ABCG2 expression." (PMID 34572902, 2021). "Though ABCG2 reporters are available, they are not useful in CSCs because the expression is regulated by the promoter demethylation in cancer." (PMID 34150761, 2021). "In the process of establishing drug‐resistant cells, ordinary cancer cells that did not express or expressed low levels of ABCG2 were killed by gem, whereas the CSC subset expressing high levels of ABCG2 were selected, forming the drug‐resistant cell line." (PMID 33934523, 2021). "Additionally, ABC transporters, such as ABCB1, ABCG2, and ABCC1, are upregulated in many cancer types." (PMID 34502100, 2021). "This is not surprising as cancer cells with the low endogenous expression of ABCG2 is sufficient to confer resistance to MLN7243." (PMID 34336849, 2021). "Our results showed that cancer cells overexpressing ABCG2 transporter were resistant to MLN7243 compared to the parental cells, while knockout of ABCG2 gene or pharmacological inhibition of ABCG2 efflux function completely reversed the drug resistance." (PMID 34336849, 2021). "Since the drug-selected MDR cancer cells may develop multiple mechanisms to exhibit MDR phenotype, HEK293 cells transfected with ABCG2 gene were used to validate our finding." (PMID 34336849, 2021). "Therefore, we used Western blotting to assess the effect of VKNG-2 on the ABCG2, PI3K- p110β and AKT protein expression in S1-M1-80 cancer cells." (PMID 33671108, 2021). "ABCG2 was originally identified as a multidrug transporter in multidrug-resistant cancer cell lines, in which none of the two MDR proteins known at that time (MDR1/ABCB1 and MRP1/ABCC1) was expressed." (PMID 33801813, 2021). "In dormant cancer cells, PEPT1 and ABCB6 were upregulated, and ABCG2 was downregulated." (PMID 33790399, 2021). "With overexpression of ABCG2 as the major difference between the two HEK293 cells, the results may be more accurate compared to the drug selected cancer cells which may have multiple MDR-related factors." (PMID 34336849, 2021). "In this study, we reported that AZ-628 significantly sensitized ABCG2-mediated MDR to ABCG2 substrate drugs at a non-toxic concentration in cancer cells." (PMID 33364237, 2020). "Among them, ABCB1, ABCG2, and ABCCs have been widely reported as MDR inducers in cancer cells." (PMID 33364237, 2020). "In contrast, cancer tissues from both the TCGA cohort and the own cohort showed similar DNA methylation levels, independent of their ABCG2 mRNA levels." (PMID 33066132, 2020). "However, findings suggest a potential of targeting cancer stem cells by using epigenetic modulators increasing DNMT activity, resulting in ABCG2 promoter hypermethylation and downregulation of ABCG2." (PMID 33066132, 2020). "Indeed, knockdown of USP4 in the cancer cell lines D121, LLC, H1299, and HCC827 increased expression of the stemness genes Oct4, Sox2, Nanog, KLF4, ABCG2, and ALDH1 in different degree in different cell lines as measured by RT-qPCR." (PMID 31936290, 2020). "In contrast, the efficacy of MCA was not significantly different (1.14-fold) in the NCI-H460 and NCI-H460/MX20 cancer cells, demonstrated that ABCG2-overexpressing cell line did not confer resistance to MCA." (PMID 32676451, 2020). "We found that sitravatinib blocks the drug efflux function of ABCB1 and ABCG2 in a concentration-dependent manner but does not significantly alter the protein expression of ABCB1 or ABCG2 in multidrug-resistant cancer cells." (PMID 31941029, 2020).
cancer (continued). "Here, we report that BMS599626 inhibits the efflux activity of ABCG2 at nontoxic, low nanomolar concentrations, thereby increasing the chemosensitivity of cancer cells to their substrate chemotherapeutic agents." (PMID 32899268, 2020). "Furthermore, there was a reduction in expression of cancer stem cell marker proteins DCLK1, CD44, CD133, Oct-4, and ABCG2." (PMID 32094348, 2020). "Since our cell proliferation studies confirmed that EC16-1/saporin is a cytotoxic compound in the cancer cell types used in the study, we subsequently determined the effect of EC16-1/saporin on the induction of apoptosis in the parental and ABCB1- and ABCG2-overexpressing cells." (PMID 32098067, 2020). "IL-17A did not increase CXCR4 (68.19% vs. 64.54%) and ABCG2 (1.96% vs. 1.52%) expression in human L3.6pl cancer cells assessed by flow cytometry." (PMID 32210079, 2020). "ABCG2 is one of the most important members of the ATP-binding cassette (ABC) transporter family, a group of membrane proteins that play a critical role in mediating multidrug resistance (MDR) in a variety of cancers, including those of the liver and lung." (PMID 31940916, 2020). "Furthermore, the tests on combination with anticancer drugs that are ABCB1 or ABCG2 substrates, showed that peptide XH-14C potentiates the cytotoxicity of paclitaxel and doxorubicin in ABCB1-overexpressing cancer cells." (PMID 32707710, 2020). "We hypothesized that combining M3814 with ABCG2 substrate-drugs can overcome MDR and provide a new treatment strategy for MDR cancer patients." (PMID 32477940, 2020). "The cytotoxic activity of ERK5-IN-1 were evaluated in vitro using a panel of cancer cell lines stabling expressing ABCB1 or ABCG2 and ERK5-IN-1 at non-toxic concentrations up to 0.4 μM were used for reversal assay in vitro." (PMID 32164732, 2020). "In this study, we validated the antagonist effect of venetoclax in ABCG2-overexpressing MDR cells, which could provide valuable information on potent, developing combination treatments for MDR cancers." (PMID 32085398, 2020). "In conclusion, our data indicated that ABCB1 and ABCG2 are unlikely to contribute significantly to the development of resistance to sitravatinib in cancer cells." (PMID 31941029, 2020). "Results showed that erdafitinib reverses multidrug resistance mediated by ABCB1, but not by ABCG2, in human cancer cell lines at subtoxic concentrations (<1 μM) and in a concentration-dependent manner." (PMID 32466597, 2020). "Moreover, the increase of ROS production in cancer cells after hyperthermia upregulated HCP-1 expression and downregulated ABCG2 expression." (PMID 30733583, 2019). "Although the clinical relevance of reversing the ABCG2-mediated MDR has been inconclusive, an appropriate modulation of ABCG2 function during chemotherapy should logically enhance the efficacy of anti-cancer agents by overcoming the MDR phenotype and/or improving their pharmacokinetics." (PMID 30890942, 2019). "Because of the relatively higher expression of the drug efflux transporter ABCG2 in cancer cells than in noncancer cells, Ko143 was found to alleviate cell‐to‐cell variability in PpIX‐FI." (PMID 31385432, 2019). "Further, diverse cancer cells may commonly exhibit increased basal expression of ABCG2 and BCRP, an important mechanism conferring multidrug resistance to chemotherapeutic drugs." (PMID 31561453, 2019). "ABCG2, one of the human ABC transporters, is an important molecule in both innate and acquired multidrug resistance, in regulation of drug bioavailability, in prognostic prediction of solid malignancies, and in protecting cancer stem cells." (PMID 30930789, 2019). "In this study, we investigated whether low concentrations of cisplatin could accelerate mitROS production in cancer cells to enhance the cytotoxicity of ALA-PDT by regulating the expression of both PEPT1 and ABCG2." (PMID 31426474, 2019).
cancer (continued). "Even though the specific role of ABCG2 in cancer progression is not yet known, this protein was shown to be overexpressed in a variety of cancers and numerous reports support its role in the maintenance and tumorigenicity of CSCs." (PMID 31191243, 2019). "Recently, symmetric bis-chalcones were demonstrated to be potent inhibitors of the breast cancer resistance protein (BCRP/ABCG2); however, the anti-cancer effects of bis-chalcones have not been investigated in GBM." (PMID 30871215, 2019). "ABCG2 and BCRP expression are elevated in stem cells and cancer cells." (PMID 31561453, 2019). "Our results indicate that TMP195 attenuates the drug efflux function, but not the protein expression of ABCB1 and ABCG2 in cancer cells." (PMID 31905792, 2019). "For the ABCG2 expression studies we have selected cell lines in which the expression of endogenous ABCG2 is very low, and these were the human embryonic kidney (HEK) 293 cells, the human HeLa cancer cells, and the dog kidney, polarizable MDCKII cells." (PMID 29749379, 2018). "Similarly, some studies concluded that lapatinib reverses ABCB1- and ABCG2-mediated MDR by directly inhibiting their transport function, contributing to the possibility of co-administration with lapatinib treated MDR cancer patient in clinic." (PMID 29455646, 2018). "We demonstrated that the expression levels of the cancer stem-like cell markers CD44, OCT4, Nanog and ABCG2, as well as the EMT regulatory factor Slug were significantly enhanced in EpCAM-overexpressing cells and reduced in EpCAM-depleted HONE1 cells compared with control cells." (PMID 29305578, 2018). "ABCG2 has thus become a CSC marker and a potential target for cancer treatment." (PMID 27343550, 2017). "Differential expression analysis between ER+ and ER– cancers identified over-expression of TTF1, LAF-4 and C-MYB (p ≤ 0.05), and between pCR vs non-pCRs, over-expression of CXCL9, AREG, B-MYB and under-expression of ABCG2." (PMID 28697743, 2017). "In addition, juxtacrine interaction between cancer cells expressing VCAM-1 and macrophages expressing VLA-4 induces expression of the CSC-like cell marker ABCG2, which relates to drug resistance, on cancer cell surfaces." (PMID 28969049, 2017). "ABCB1 and ABCG2, which are important ATP-binding cassette (ABC) transporters, contribute to multidrug resistance in tumor chemotherapy through transporting anti-tumor drugs to the outside of cancer cells." (PMID 28438180, 2017). "In addition, the expression of ABCG2, MDR-1,p-GP and GST-π, four key drug resistance related proteins involved in 5-fluorouracil (5-FU) resistance for multiple cancer cells, were significantly increased in the resistant cell lines." (PMID 29137307, 2017). "Another important piece of information regarding normal tissue toxicity when bypassing ABCG2 concerns studies where cancer patients have received novel types of topoisomerase inhibitors that are not substrates for ABCG2." (PMID 28880238, 2017). "As ABCG2 expression in primary SCC is much lower than ABCB1, treatment of lung aggregate cultures with rhWnt5a induced changes in drug transporter pattern in vitro that was highly similar to what was detected in primary cancer samples of squamous histology." (PMID 28340578, 2017). "ABCG2, member of ATP-binding cassette (ABC) transporter family, is known as crucial regulator related to multi-drug resistance in human tumors and has recently been putatively studied as human carcinoma cell biomarker." (PMID 28029654, 2017). "c-MYC, ABCG2, NESTIN and OCT4 have important role in cancer progression." (PMID 27054115, 2016). "Furthermore, the MtDP PC3 cells were resistant to therapeutic treatments and contained greater cancer stem cell-like subpopulations: CD44+, ABCG2+, side-population and ALDHbright." (PMID 27248169, 2016).
cancer (continued). "However, only three major ABC drug transporters, including P-glycoprotein (P-gp; ABCB1), multidrug resistance protein 1 (MRP1; ABCC1) and ABCG2 (BCRP; MXR), are believed to seriously affect cancer chemotherapy." (PMID 26959063, 2016). "On the basis of our observations of ABCG2 immunoreactivity in the included CRC samples, we defined scoring guidelines for future studies to validate the predictive value of ABCG2 immunoreactivity in cancer tissue." (PMID 27257141, 2016). "However, the cancer cell lines showed substantial differences in the promoter methylation status of the ABCB1 and ABCG2 promoters." (PMID 27689338, 2016). "Furthermore, NRF2 target genes were overexpressed in various cancer cells after PDT, which include HO-1, GCLC and GCLM subunits of GCL, NQO1, and ABCG2." (PMID 26516076, 2015). "Initially, ABCG2 was considered a stem cell marker in bone marrow and subsequently it became a potential stemness marker in HCC, as it was detected in HCC and various cancer types." (PMID 26064420, 2015). "As reported, ABCG2 and ABCC1 transporters also lead to cancer MDR." (PMID 26296969, 2015). "Recent research of cancer stem cells (CSCs) in CRC brought the renaissance of the MDR-phenomenon, since the tumor repopulating side population of the resistant CSCs are expressing more ABC-transporters, especially ABCG2 (MXR, BCRP)." (PMID 25885226, 2015). "FL118, for example, is a unique camptothecin analogue that is not effluxed by either ABCG2 or P-gp, and is able to overcome resistance to irinotecan and topotecan in cancer xenograft models." (PMID 26714461, 2015). "In this context, ABCG2 is an ABC transporter; an inhibition of ABCG2 may reverse drug resistance of cancer cells, suggesting that miR-328 is a novel therapeutic approach for antimetastatic therapy." (PMID 26064956, 2015). "In addition to this, nilotinib significantly potentiates the anti cancer activity of PTX in ABCB1, ABCC10 and DOX in ABCG2 tumor xenograft model." (PMID 25191874, 2014). "Therefore, much effort has been devoted to developing ABC transporter inhibitors such as ABCB1 and ABCG2 in the hope that they would kill drug resistance cancer cells." (PMID 25111504, 2014). "Overall, it is possible that masitinib, in combination with antineoplastics that are ABCG2 substrates, may be used in the treatment of certain MDR cancers." (PMID 24626598, 2014). "Comparing tumor and normal tissues, three of the five analyzed genes showed a significant lower expression in tumors than in healthy control tissues (ABCB1, p<0.0001; ABCC2, p<0.005; ABCG2, p<0.0001), whereas ABCC1 expression was significantly up-regulated in the carcinomas (p<0.0001)." (PMID 25275603, 2014). "Finally, LABCG2 belongs to the same subfamily as mammalian ABCG2, a well-characterized PS transporter that also pumps drugs conferring a MDR phenotype in cancer cells." (PMID 23638200, 2013). "To date, a few miRNAs (miR-520 h, -519c, -328, -181a, & -487a) have been identified by different research groups independently to regulate ABCG2 expression by interacting directly with ABCG2 3′UTR and to determine the sensitivity of cancer cells to chemotherapeutic drugs." (PMID 24358977, 2013). "Furthermore, the expression of ATP-binding cassette sub-family G member 2 (ABCG2), which is an important gene for chemoresistance, was demonstrated to be reduced in CD133+ cancer stem cells following combined treatment." (PMID 24223665, 2013). "Furthermore, the ABC transporters (ABCG2, ABCB1) have been proposed to be expressed by quiescent cancer stem cells, which allows them to survive cytotoxic or targeted therapies leading to relapse." (PMID 23174366, 2012). "Our data demonstrated that there exist ABCG2+ cells in NPC cells, but ABCG2 alone is not sufficient for isolating cancer stem cells in 5–8F NPC cells." (PMID 22209971, 2012). "Marked differences in expression of ABCG2 and V-ATPase were found between metastatic and non-metastatic groups in the same carcinomas (P < 0.0001)." (PMID 23244569, 2012).
cancer (continued). "The ABCG2+ cells and the non-luminal-like cancer cells are more similar to stem cells in overall gene expression than the luminal-like cancer cells." (PMID 21605402, 2011). "Taken together, ABCG2 is considered as one of the critical factors that may affect the efficacy of PDD and PDT of human cancer." (PMID 24310600, 2011). "In this study, we show that SP cells express more ABCG2 than non-SP cells, supporting the concept that cancer stem-like cells highly express ABCG2, as seen in other tumour types." (PMID 20354527, 2010). "Furthermore, molecules that facilitate drug resistance in cancer cells like ABCB1 and ABCG2 were added to the list of putative CSC markers as well as proteins for which no involvement in stemness or cancerogenesis was known, e.g. CD20." (PMID 20459772, 2010). "Recently, ABCG2 was identified in cancer cell lines selected with mitoxantrone that do not express Pgp and MRP1." (PMID 20653978, 2010). "The results above indicated that vandetanib could enhance the sensitivity of MDR cancer cells to certain ABCC1 and ABCG2 substrate anticancer drugs." (PMID 19390592, 2009). "Later studies determined that ABCG2 expression is not unique to drug resistant cancer cells, but is also expressed in a wide variety of stem cells and in numerous adult tissues." (PMID 19107196, 2008). "Alternatively, lower concentrations of lapatinib might be sufficient to inhibit ABCG2 activity in cancer cells, but not in organs expressing higher levels of ABCG2 (e.g. liver)." (PMID 41505030, 2026). "During chemotherapy treatment, certain cancer cells upregulate the expression of ATP-binding cassette (ABC) efflux transporters, including P-glycoprotein (P-gp/ABCB1), multidrug resistance protein 2 (MRP2/ABCC2), and breast cancer resistance protein (BCRP/ABCG2)." (PMID 40723808, 2025). "Importantly, QB1561 showed lower IC50 values in parent cancer cell lines with minimal ABC transporter expression compared to resistant cells, suggesting that it may be a weak substrate of ABCB1 or ABCG2." (PMID 40066335, 2025). "In cisplatin-resistant OSCC, TGF-β1 modulates the cancer cell stemness where it inhibited the tumor suppressor gene FOXO3a via AKT pathway, a non-canonical, SMAD-independent pathway, resulting in the increased expression of SOX2 and ABCG2, which are markers of stemness." (PMID 40176914, 2025). "Additionally, hyptolide treatment increased ABCG2 expression and reduced P-gp expression in cisplatin-resistant CP1#1 and CP1#2 cells, which is a possible therapeutic mechanism for overcoming drug-resistant cancer cells." (PMID 40506749, 2025). "Moreover, histone H3K9 acetylation has been demonstrate to induce ABCG2 gene transcription in multidrug resistant cells, further supporting that the nuclear translocation of PDC may confer MDR in cancer cells." (PMID 40612109, 2025). "Therefore, ABCG2 expression most likely does not affect the processes related to clinical aggressiveness of the disease in this type of cancer." (PMID 39457707, 2024). "Furthermore, immunoassays for HTC were developed to distinguish cancer cells from stromal cells using the CK8/18 antibody cocktail and to distinguish cells with a multidrug-resistant phenotype from sensitive cells using the ABCB1, ABCC1 and ABCG2 antibodies." (PMID 39337925, 2024). "Breast cancer resistance protein (BCRP/ABCG2), multidrug resistance protein 1 (MRP1/ABCC1), and P-gp are the ATP-binding cassette (ABC) transporter family members that carry out drug efflux and their overexpression contributes to the development of chemoresistance in cancer cells." (PMID 39061884, 2024). "Similarly, HS-173 at the same concentration did not re-sensitize ABCG2-overexpressing S1-MI-80 cancer cells to the drug substrates of ABCG2 (mitoxantrone, topotecan or SN-38)." (PMID 37048130, 2023).